MCTP2 (multiple C2 and transmembrane domain containing 2)
Description:
Might play a role in the development of cardiac outflow tract.
Synonyms: FLJ11175; FLJ33303
Tractability: Antibody: UniProt predicts a signal peptide or a membrane-spanning region. PROTAC: ubiquitination databases record sites on it; its protein half-life has been measured.
Gene: Protein-coding gene on chromosome 15 (94,231,526 to 94,483,952, forward strand). Ensembl gene ENSG00000140563.
Subcellular location: Membrane
Subcellular location (Human Protein Atlas): Cytosol; Nucleoplasm
Gene Ontology:
Molecular function: calcium ion binding; calcium-dependent phospholipid binding
Biological process: calcium-mediated signaling; regulation of neurotransmitter secretion
Cellular component: cytosol; membrane; nucleoplasm; synaptic vesicle membrane; cytoplasm
Genetic constraint (gnomAD): Loss-of-function variants: 71 observed, 65.12 expected, observed/expected ratio (o/e) 1.09, 90% interval 0.9 to 1.33. The upper end of that interval is the gene's LOEUF score, 1.33, which puts it in group 5 of 6, group 1 being the genes least tolerant of losing a copy. Missense variants: 813 observed, 762.83 expected, observed/expected ratio (o/e) 1.07, 90% interval 1 to 1.13. Synonymous variants: 277 observed, 290.99 expected, observed/expected ratio (o/e) 0.95, 90% interval 0.86 to 1.05.
Homologues: Orthologues: macaque MCTP2 (98% identical), chimpanzee MCTP2 (94% identical), pig MCTP2 (93% identical), dog MCTP2 (93% identical), mouse Mctp2 (89% identical), rat Mctp2 (88% identical), guinea pig MCTP2 (88% identical), rabbit MCTP2 (88% identical), tropical clawed frog mctp2 (64% identical), zebrafish mctp2a (46% identical), zebrafish mctp2b (44% identical), Drosophila melanogaster Mctp (34% identical), and 1 more. Paralogues in human: MCTP1 (47% identical).
Diseases named in the same sentence as MCTP2 in open-access papers:
MCTP2 is named in the same sentence as 18 diseases in open-access papers, as found by Europe PMC text mining. Sharing a sentence is not in itself a finding about the gene and the disease. The quoted sentences say what the papers report.
gastric cancer (3 papers, 2020 to 2024). A primary or metastatic malignant neoplasm involving the stomach. "In gastric cancer, the circular RNA MCTP2 impedes cisplatin resistance by inducing Myotubularin Related protein 3 (MTMR3) expression via miR-99a-5p." (PMID 39293372, 2024). "TRIM66 expression has been shown to promote malignant progression in several types of cancer, including HCC, and MCTP2 inhibited cisplatin resistance in gastric cancer." (PMID 36035299, 2022).
schizophrenia (2 papers, 2013 to 2020). A major psychotic disorder characterized by abnormalities in the perception or expression of reality. "Among possible targets of these eRNA candidates are ARHGEF38 and SH3YL1, which have been linked to bipolar disorder and suicide, GLRA1 and MCTP2 were found to be associated with schizophrenia, and CHIR-B3, MHCIA7, MHCIY as well as MICA are genes involved in the immune system." (PMID 32854615, 2020). "Interestingly, this region contains the MCTP2 gene previously associated with schizophrenia in samples consisting of Norwegian, Swedish and Danish subjects." (PMID 23460800, 2013).
colorectal cancer (1 paper, 2023). A primary or metastatic malignant neoplasm that affects the colon or rectum. "There are few studies on the DPYD, ARHGEF6, MCTP2 and SPN genes in AML, but these genes are known to be differentially expressed in other tumors, such as colorectal cancer, lung cancer and hepatocellular carcinoma." (PMID 36879313, 2023).
congenital heart disease (1 paper, 2022). A heart disease that is present at birth. "Copy number variation encompassing MCTP2 has been shown to cause congenital heart disease inclusive of mitral atresia or stenosis, and absent endocardial cushions were observed in morpholino knockdowns of Mctp2 in Xenopus embryos." (PMID 35132965, 2022).
major depression (1 paper, 2009). "The gene in this region, MCTP2 (multiple C2 domains, transmembrane 2), is expressed in the brain and has been implicated in linkage and association studies of abdominal fat and major depression." (PMID 19772629, 2009).
pulmonary hypertension (1 paper, 2019). Increased pressure within the pulmonary circulation due to lung or heart disorder. "Interestingly, the differential expression of CAST and MCTP2, found in the present study, could be linked with two pathological phenotypes, pulmonary hypertension and overweight, both of which associated with CMS, as shown in the present study." (PMID 31417607, 2019).
cancer (2 papers, 2022 to 2023). A tumor composed of atypical neoplastic, often pleomorphic cells that invade other tissues. "Microarray analysis of cancer tissues from AOM/DSS and AOM/DSS/Ab mice revealed profound differences in the expression of genes associated with mast cells, namely Mctp1, Mctp2, Mctp4, Cma1, Fcer1a, Pla2g2e, and Cpa3." (PMID 37185713, 2023).
heart disease (1 paper, 2022). "Congenital heart disease is an example where causative mutations in MCTP2 gene are known to be only dominant, but found to be recessive in a consanguineous cohort." (PMID 35718832, 2022).
neurodevelopmental disorder (1 paper, 2022). A behavioral and cognitive disorder with onset during the developmental period that involves impaired or aberrant development of intellectual, motor, or social functions. "More recently, heterozygous frameshift and stop gain variants in MCTP2 were identified in two patients with left sided defects and one patient with TGA, and also as a homozygote in one patient with AVS, PVS and neurodevelopmental disorder." (PMID 35737725, 2022).
MCTP2 also shares sentences with these, for which no sentence is quoted: Obesity (2 papers); atrial fibrillation (1); Bardet-Biedl syndrome (1); bipolar disorder (1); cardiovascular diseases (1); hepatocellular carcinoma (1); lung carcinoma (1); mitral atresia (1); stenosis (1).